AQP4 (aquaporin 4)
Diseases named in the same sentence as AQP4 in open-access papers (continued):
Sharing a sentence is not in itself a finding about the gene and the disease.
Hydrocephalus (continued). "Alterations in the glymphatic system associated with the downregulation or redistribution of AQP4 appear to play a role in the etiology of idiopathic normal-pressure hydrocephalus, but it remains unclear whether there is are direct associations between the glymphatic system, AQP4, and hydrocephalus." (PMID 39839745, 2024). "Thus, the increase in AQP4 expression under sulfatide deficient conditions presented here, might represent an adaptive response to increases in CSF, i.e., hydrocephalus." (PMID 36613677, 2022). "Additionally, altered expression or distribution of AQP4 has been associated with hydrocephalus." (PMID 34575909, 2021). "However, AQP4 presence in the CSF has also been proposed as a diagnostic biomarker of hydrocephalus type; additionally the sites and mechanisms of CSF reabsorption are relevant to the pathophysiology of hydrocephalus." (PMID 27379319, 2014). "Moreover, AQP4 deficit has been shown to cause hydrocephalus in experimental models." (PMID 25165051, 2014). "Meanwhile, the survival rate of AQP4−/−-OH mice that developed symptoms of hydrocephalus early, by the first postnatal week, dropped drastically to 50% by days 11–13; all died before reaching 50 days of age." (PMID 41226330, 2025). "The kaolin-induced hydrocephalus rat model’s pathophysiology is mainly focused on neuroinflammatory changes and alterations of AQP4, the brain’s most abundant water channel that regulates water homeostasis." (PMID 40046632, 2025). "Identifying the cellular source of the Spp1 gene in the AQP4−/−-NH/CD1 mouse was impossible, given the loss of the obstructive hydrocephalus phenotype." (PMID 41226330, 2025). "While maintaining the AQP4−/−/CD1 colony, 9% of the offspring of the AQP4−/− mice sporadically developed hydrocephalus." (PMID 41226330, 2025). "Meanwhile, the survival rate of AQP4−/−-OH mice that developed symptoms of hydrocephalus early in the first postnatal week dropped drastically to 50% by days 11–13, with all animals dying before reaching 50 days of age." (PMID 41226330, 2025). "Taken together, our findings indicate that AQP4 deficiency alters the molecular and cellular environment around the Sylvian aqueduct, compromising ependymal integrity and microglial reparative activity, which may predispose to aqueductal stenosis and hydrocephalus in a subset of animals." (PMID 41226330, 2025). "AQP4 knockout mice exhibited greater ventricular enlargement and elevated ICP compared to wild-type mice in an experimental model of obstructive hydrocephalus, suggesting a function for AQP4 in CSF absorption." (PMID 39944892, 2025). "In an animal hydrocephalus model, EPO treatment significantly mitigated the dilation of the cerebral ventricles in obstructive hydrocephalus by augmenting the expression of AQP4." (PMID 39944892, 2025). "Several studies have reported elevated expression of AQP4 in connection with hydrocephalus, including congenital hydrocephalus in Texas rats, idiopathic communicating internal hydrocephalus in dogs, and inflammatory communicating hydrocephalus in rats." (PMID 39944892, 2025). "Further study with the simultaneous evaluation of AQP1 and AQP4 expression will be helpful to confirm the role of AQP4 in the development of hydrocephalus after IVH." (PMID 37208490, 2024). "A rat study involving Sprague-Dawley rats demonstrated increased AQP4 expression after mild hydrocephalus induction with kaolin injection." (PMID 39364470, 2024). "The findings in these studies suggested that the upregulated expression of AQP4 in the periventricular tissue prompted water movement into the ventricles and the formation of hydrocephalus after experimental IVH." (PMID 37208490, 2024). "Then the increased expression of AQP4 in the ependymal cells facilitated osmotically driven water movement from the brain parenchyma into the ventricle and the development of hydrocephalus." (PMID 37208490, 2024).
Hydrocephalus (continued). "AQP4 located in the periventricular area mediated the effect of iron overload on hydrocephalus after IVH." (PMID 37208490, 2024). "The dual effects on AQP4 indicate that TGN-020 is a promising agent for the treatment of hydrocephalus after IVH." (PMID 37208490, 2024). "Further, in our study, blocking AQP4 by injection of TGN-020 alleviated ventricular dilatation after IVH, which indicated that AQP4 contributed to the development of hydrocephalus." (PMID 37208490, 2024). "Taken together, these studies highlight the dynamic changes in the expression of AQP1 and AQP4 during the different stages of hydrocephalus." (PMID 38337135, 2024). "The increase in AQP1 and AQP4 expression during hydrocephalus can be a compensatory mechanism to increase fluid clearance in the brain." (PMID 39364470, 2024). "Our study showed an increased expression of AQP4 in the periventricular area from day 7 to day 28 in hydrocephalus rats after IVH, which was consistent with previous literatures." (PMID 37208490, 2024). "In mice lacking AQP4, a prolonged and stronger presence of these CD11c microglia (AQP4-Aq) will be essential for compensating for the normal development of the ependymal epithelium, thus preventing the onset of hydrocephalus." (PMID 38956598, 2024). "AQP4 dysfunction occurring as a result of NMOSD can cause decreased cerebrospinal fluid (CSF) resorption, which can exacerbate hydrocephalus." (PMID 39135307, 2024). "Several studies reported an increase in the expression of AQP4 in rat models with inherited and kaolin-induced hydrocephalus." (PMID 37208490, 2024). "A higher AQP4 level was found in the ECs after subarachnoid hemorrhage, and the expression level of AQP4 was related with the severity of hydrocephalus." (PMID 37238624, 2023). "Aquaporin-4 (AQP4) plays a crucial role in brain water circulation and is considered a therapeutic target in hydrocephalus." (PMID 36982724, 2023). "Further research will be needed to investigate possible neuroprotective mechanisms against hydrocephalus for such AQP4 overexpression." (PMID 36982724, 2023). "In hydrocephalus, the main function of AQP4 is compensatory: functioning as an alternative pathway for CSF uptake through ependymal cells." (PMID 37397456, 2023). "The analysis of the molecular mechanism by which AQP4 can generate an improvement in hydrocephalus can be complex." (PMID 36982724, 2023). "A higher expression of AQP4 has also been described in the ventricular walls of hydrocephalic pediatric cases and in animal models of congenital and experimental hydrocephalus, where it has been considered to play a protective role." (PMID 36982724, 2023). "AQP4 is present in astrocytes and, thus, has been proposed as a therapeutic target in hydrocephalus." (PMID 36982724, 2023). "In some brain tumor, and hydrocephalus models, AQP4 has been proved to be correlated with single ADC values or multi-parameter ADC values, but such a rule cannot be verified in our experimental model." (PMID 36605551, 2022). "We showed that FOXJ1-Cre;CEP164fl/fl mice with hydrocephalus still demonstrated sustained glymphatic transport and normal AQP4 expression along capillaries." (PMID 35248089, 2022). "The parenchymal fluid contributes to the glymphatic system, and plays a fundamental role in pediatric hydrocephalus, with aquaporin 4 (AQP4) as the primary facilitator of these fluid movements." (PMID 35346374, 2022). "Using flow cytometry, we demonstrated that the GFAP-positive vesicles produced by glial cells colocalized mostly with AQP4 and that AQP4 levels were higher in samples from patients with obstructive hydrocephalus." (PMID 35346374, 2022). "This manuscript is a focused review of the current research landscape on AQP4 as a possible biomarker for gliogenesis and its influence in pediatric hydrocephalus, emphasizing reactive astrogliosis." (PMID 36142348, 2022).
Hydrocephalus (continued). "In rats with hydrocephalus, the fluorescence signal of AQP4 was strongly polarized to the perivascular foot of astrocytes." (PMID 36226316, 2022). "Three of the most well recognized and studied proteins implicated in hydrocephalus are NKCC1, Aquaporin-1 (AQP-1), and Aquaporin-4 (AQP-4)." (PMID 35306341, 2022). "In human hydrocephalus samples, AQP4 fluorescence signals were present throughout the astrocyte membrane." (PMID 36226316, 2022). "AQP4 channels have been reported to increase after two weeks of hydrocephalus to facilitate CSF absorption from the ventricle into the parenchymal extracellular space." (PMID 36613677, 2022). "The searching terms were “hydrocephalus and gliogenesis”, “reactive astrogliosis and white matter and hydrocephalus”, “AQP4 and gliogenesis”, “AQP4 and brain development”, and “AQP4 and neurogenesis”." (PMID 36142348, 2022). "AQP4-null animals in models of vasogenic edema, including cortical freeze injury, brain tumor, brain abscess, and hydrocephalus, show brain swelling and the clinical prognosis is poor." (PMID 35260880, 2022). "In contrast to other types of hydrocephalus, the decrease in AQP4 in iNPH and Alzheimer's disease is related to the progressive loss of perivascular units responsible for water exchange." (PMID 36204139, 2022). "AQP4 demonstrates its impact on the occurrence and progression of hydrocephalus in a number of animal models of the condition." (PMID 36204139, 2022). "In fact, it has been shown that 40% of AQP4 knockout mice have VZ disruption, with 10% also showing hydrocephalus due to stenosis of the Sylvian aqueduct." (PMID 35346374, 2022). "AQP4 contributes to the development of hydrocephalus by hypoxia in aged mice, reproducing such principal characteristics of the disease." (PMID 34575909, 2021). "Experiments with knockout mice showed an accelerated progression of this pathology, while, on the contrary, AQP4 upregulation has been suggested to contribute to early hydrocephalus development." (PMID 33499944, 2021). "Viewed together, our AQP1 and AQP4 data correlates with a reduced magnitude of hydrocephalus after USSC treatment consistent with improved CSF fluid homeostasis." (PMID 33897371, 2021). "While human studies are more limited, it was also found that AQP4 protein levels in CSF were elevated in communicating hydrocephalus samples compared to controls." (PMID 34440681, 2021). "Aqp4−/− mice show sporadic brain ventricular enlargement, accelerated progression of induced hydrocephalus, and increased basal brain water accumulation, suggesting that AQP4 is critical for controlling whole-brain water homeostasis." (PMID 34002021, 2021). "Here we have uncovered Kidins220-SNX27-retromer as a regulatory pathway for brain AQP4 expression and its involvement in brain ventricular enlargement and hydrocephalus." (PMID 34002021, 2021). "Upregulation of AQP4 is a homeostatic countermeasure employed in the setting of hydrocephalus in order to help to disburse accumulated CSF and reduce high ICP." (PMID 34440681, 2021). "Compounds modulating AQP4 function are under development for hydrocephalus disease but have yet to enter clinical trials." (PMID 33499944, 2021). "In a rodent model where hydrocephalus is induced by l-alysophosphatidylcholinestearoyl injection, upregulation in AQP4 expression in astrocytes, both on astrocytic endfeet and on the entire membrane of the astrocyte was recorded." (PMID 30691235, 2019). "Hydrocephalus upregulates brain water channel AQP4 at the brain–CSF interfaces as well as surrounding astrocyte end-feet and subpial layers in hydrocephalus animals." (PMID 29982881, 2018). "It is noted that EPO treatment upregulates AQP4 expression and reduces dilated cerebral ventricles in kaolin-induced model of obstructive hydrocephalus in rat pups." (PMID 29982881, 2018).
Hydrocephalus (continued). "Significant increases in AQP4 expression that occur along animal’s aging contribute to produce a considerably worse hydrocephalus situation related with hypoxic events, with impairment of the cognitive function." (PMID 30583728, 2018). "In this study, we investigate a neuroprotective agent, erythropoietin (EPO), in animal hydrocephalus model and its potential reversal effects on hydrocephalus by altering the expression of aquaporin-4 (AQP4)." (PMID 29982881, 2018). "This in turn would reduce hydrocephalus by upregulating AQP4 expression at major junctions of fluid compartments." (PMID 29982881, 2018). "Water effluxes via glial-vascular pathway or “glymphatic pathway” by modulating AQP4 channel is an attractive therapeutic target for potential molecular treatment of hydrocephalus." (PMID 29982881, 2018). "In order to identify a critical role of AQP4 in progression of hydrocephalus, we tried to gain insights into the potential mechanisms of protective effect of EPO." (PMID 29982881, 2018). "Present study examines the role for EPO in modulating AQP4 water channels in experimental hydrocephalus." (PMID 29982881, 2018). "Compared to normal control tissue, the choroid plexus in hydrocephalus cases exhibited more pronounced basolateral AQP4 immunoreactivity and increased AQP1 immunoreactivity in the cytoplasm and at the apical plasma membrane." (PMID 28184993, 2017). "AQP4 appears to have a protective role in cases of hydrocephalus, given its role in CSF absorption in cerebral vasculature." (PMID 28036023, 2016). "This notion is also supported by the observation that AQP4 null mice exhibit a more severe form of hydrocephalus with larger ventricular distension and pressure elevation after kaolin injection, than mice with unimpaired AQP4 expression." (PMID 27357498, 2016). "The mean total AQP4 quantity (325.8 ng) in dogs with internal hydrocephalus before surgery was significantly different from control dogs (32.12 ng, P < 0.0001)." (PMID 27357498, 2016). "AQP4-null mice showed significant ventriculomegaly after kaolin injection to reproduce obstructive hydrocephalus, increasing intracranial pressure by 2%–3%." (PMID 28036023, 2016). "The ependymal lining is frequently destroyed in hydrocephalus and AQP4 can, therefore, leak more easily from the parenchyma to the CSF via the ECF." (PMID 27357498, 2016). "Up-regulation of AQP4 channels has been documented in a variety of pathological processes in the brain that result in fluid overload, including internal hydrocephalus." (PMID 27357498, 2016). "In rats with inherited and kaolin-induced hydrocephalus, an increase in AQP4 mRNA- and protein levels within the periventricular parenchyma was reported post-induction." (PMID 27357498, 2016). "After kaolin-induced hydrocephalus in wild-type mice, AQP4 expression was increased 3–4 weeks post-injection, with highest levels in the perivascular areas, parietal cerebrum and hippocampus, ependymal lining, and glia limitans." (PMID 28036023, 2016). "Studies in animal models, in which internal hydrocephalus has been induced by obstructing the cerebrospinal fluid pathways, have documented an up-regulation of the concentrations of aquaporin-4 (AQP4) in the brain." (PMID 27357498, 2016). "The concentrations of AQP4 and IL-6 were increased in the cerebrospinal fluid of dogs with hydrocephalus compared to controls." (PMID 27357498, 2016). "Studies in animal models, in which internal hydrocephalus has been induced by injection of kaolin into the subarachnoid space, documented an up-regulation of AQP4 in the periventricular white matter and cerebral cortex." (PMID 27357498, 2016). "In a rat hydrocephalus model using L-α-lysophosphatidylcholine stearoyl injection, a continuous elevation of AQP4 in the periventricular region was seen throughout 30 days." (PMID 26526878, 2015). "The study further conjectured that the up-regulation of AQP4 would facilitate water clearance in hydrocephalus." (PMID 26526878, 2015).
Hydrocephalus (continued). "The molecular mechanisms driving the accumulation of cerebrospinal fluid in hydrocephalus are poorly understood, but it is plausible to investigate the role of AQP4 channels in facilitating fluid exchange between the capillary bed and the extracellular space." (PMID 26526878, 2015). "During the onset of kaolin-induced hydrocephalus, AQP4 levels in the periventricular region were decreased at 48 hours, followed by a gradual recovery." (PMID 26526878, 2015). "In hydrocephalus produced by cisternal kaolin injection, AQP4-null mice demonstrated ventricular dilation and raised intracranial pressure, which were both significantly greater when compared to wild-type mice." (PMID 24817998, 2014). "Impairment of AQP4-dependent brain water clearance was suggested as the mechanism of injury in cortical freeze-injury, brain tumor, brain abscess and hydrocephalus." (PMID 24817998, 2014). "In the present work, the expression of AQP4 in the cerebrospinal fluid (CSF) in control and congenital human hydrocephalus infants (obstructive and communicating), was analysed by Western-blot and enzyme immunoassay (ELISA)." (PMID 23659378, 2013). "The aim of the present work is to examine the expression of AQP4 in the CSF in patients with congenital obstructive and communicating hydrocephalus." (PMID 23659378, 2013). "ELISA also, showed that AQP4 was also greater in communicating hydrocephalus when compared to the control (χ 22 = 7.14 p < 0,05) and when compared to obstructive hydrocephalus (χ 22 = 4.32 p < 0.05)." (PMID 23659378, 2013). "Despite that, in results presented here the AQP4 was increased in the CSF of the hydrocephalus samples taken from the lateral ventricle compared to control CSF taken from lumbar puncture." (PMID 23659378, 2013). "Western-blot showed higher values for AQP4 than controls in communicating hydrocephalus (communicating: 38.3%, control: 6.9% p < 0.05) although the increase was not significant in obstructive hydrocephalus (obstructive: 14.7%)." (PMID 23659378, 2013). "The AQP4 quantification by ELISA also showed that, the mean concentration of AQP4 in CSF was significantly higher in communicating hydrocephalus (communicating: 11.32 ± 0.69 ng/ml, control: 8.61 ± 0.31 ng/ml; p < 0.05)." (PMID 23659378, 2013). "Only one study reported sporadic cases of obstructive hydrocephalus in a subgroup of AQP4-knockout mice." (PMID 23659378, 2013). "Further, knock-out of aquaporin 4 has been shown to exacerbate hydrocephalus in kaolin-induced hydrocephalus, suggesting the importance of aquaporin 4 in water clearance in hydrocephalus." (PMID 22291910, 2012). "Further studies are necessary to investigate changes in aquaporin 4 expression and other signaling mediators downstream of the Ro1 receptor in the development of hydrocephalus in the Ro1 model." (PMID 22291910, 2012). "One study connected the different functions of AQP4 to hydrocephalus by reporting a 9.6% rate of sporadic obstructive hydrocephalus as consequence of disorganised ependyma and aqueductal stenosis in AQP4-null mice." (PMID 21054845, 2010). "We consider that changes in ADC values and AQP4 represent phases of ICP changes following hydrocephalus development." (PMID 21054845, 2010). "Obstructive hydrocephalus, produced by kaolin injection into the cistern magna, induced faster ventricular enlargement in AQP4 knock-out than in wild-type mice." (PMID 21119879, 2010). "Using magnetic resonance diffusion-weighted imaging, the degree of experimental hydrocephalus was correlated with up-regulation of AQP4 and the periventricular apparent diffusion co-efficient." (PMID 20860832, 2010). "The finding of increased AQP4 expression in various models of hydrocephalus has been interpreted as a compensatory mechanism to allow for transependymal/parenchymal CSF absorption." (PMID 20860832, 2010).